ENSG00000286476 (novel transcript)
Gene: Long non-coding RNA gene on chromosome 12 (77,129,178 to 77,163,638, forward strand). Ensembl gene ENSG00000286476.
Gene Ontology:
Biological process: RNA processing
Cellular component: nucleolus